IDH1 (isocitrate dehydrogenase (NADP(+)) 1)
Diseases named in the same sentence as IDH1 in open-access papers (continued):
Sharing a sentence is not in itself a finding about the gene and the disease.
glioma (continued). "The AKT-mTOR signaling pathway activation by IDH1 R132H will provide new evidence on future application of other combined targeted therapy for glioma with IDH1 R132H mutations." (PMID 28052098, 2017). "In low grade gliomas IDH1 mutations are the earliest genetic alteration whereas higher grade gliomas are associated with IDH1 copy number variations." (PMID 29312620, 2017). "In gliomas, when the IDH1 mutation is present, it is typically found throughout the entirety of otherwise heterogeneous tumors, which makes targeting vulnerabilities conferred by mutant IDH1 very appealing." (PMID 28178660, 2017). "Numerous studies have reported that glioma patients with isocitrate dehydrogenase 1(IDH1) R132H mutation are sensitive to temozolomide treatment." (PMID 28427200, 2017). "We demonstrate that DLR is a useful and accurate tool for predicting IDH1 mutation status in low-grade gliomas." (PMID 28710497, 2017). "Up to 90% of grades II-III gliomas contain a single mutant isocitrate dehydrogenase 1 (IDH1) allele." (PMID 28178660, 2017). "IDH1 mutations change the function of the enzymes, increase DNA methylation and correlate with improved prognosis in glioma." (PMID 29046615, 2017). "One of the most exciting discoveries of the past years in the field of cancer metabolism was the one of IDH1/2 mutations in gliomas and acute myeloid leukemia." (PMID 27752843, 2017). "Except for the classical subtype of GSE16011 (the median of DCTD expression in IDH1-mutated glioma is higher than the ones with wild-type IDH1), all the analysis results were corresponding to above conclusions." (PMID 28912488, 2017). "Sabit, H. reported that in clinical specimens of glioma by the levels of mutation of IDH1 R132H occurring increased with higher grade of invasion of glioma." (PMID 28052098, 2017). "Somatic mutations in the gene that encodes IDH1 have been reported to be present in some glioma subtypes in high frequencies." (PMID 31548536, 2017). "The data demonstrate that XAF1 promoter methylation determined by MS-HRM is a robust and precise indicator of IDH1 mutations in grade III gliomas." (PMID 28122345, 2017). "Gliomas associated with IDH1 mutation are considered to be a genetically distinct entity predicting better survival." (PMID 26738856, 2017). "Then, we demonstrated that 51.8, 37.3, and 54.2 % of high-grade gliomas in our collection (including IDH1-mutated tumors) were promoter methylated as determined by HRM, MSP, and PSQ, respectively, indicating HRM and PSQ provided comparable results." (PMID 27158275, 2016). "In this report, we compared the clinical and molecular characteristics of glioma patients harboring IDH1 and IDH2 mutations." (PMID 27245697, 2016). "Other studies have shown that oligodendroglial tumors and glioma with mutated IDH1 are strongly associated with the chromosome 8q24.21 risk variant (rs55705857)." (PMID 26839018, 2016). "Somatic mutations in IDH1 or IDH2 result in the accumulation of an oncogenic metabolite, 2-hydroxyglutarate (2-HG), which can inhibit TET activity, and IDH1/2 mutations are strongly associated with the hypermethylator phenotype in glioma and AML." (PMID 27977763, 2016). "Following the first observation of recurrent IDH1 mutation in glioblastoma, several groups have begun to clarify the frequency and distribution of IDH1 mutation across all brain tumors, including gliomas and other subtypes." (PMID 26858939, 2016). "Our data indicates, that nuclear ATRX loss in glioma is a helpful marker for predicting both, IDH1/2 and H3F3A mutations status in tumors." (PMID 27311324, 2016). "Genomic analysis demonstrated that in more than 70% of patients with low or high-grade gliomas, the mutation of amino acid 132 of IDH1 occurred, and in 12% of the GBM samples." (PMID 27338365, 2016).
glioma (continued). "For instance, the reduction of Glu levels resulting from the decreased activity of the branched–chain amino acid transaminase 1 (BCAT1) enzyme has been suggested to be strongly associated with the pathogenesis of the IDH1 mutated gliomas." (PMID 26820720, 2016). "Rs55705857-G allele showed the strongest association with IDH1 mutation in “all gliomas” group (53% vs. 81%, for A/A and A/G, respectively; p = 0.001, determined by chi-square test)." (PMID 27282637, 2016). "Glioma CIMP tumors are strongly associated with an IDH1 gain of function mutation, resulting in production of an oncometabolite that inhibits DNA demethylation enzymes (TETs)." (PMID 27879658, 2016). "IDH1/2 mutations dominate in WHO grade II/III gliomas (also called as lower grade gliomas) and secondary GBM." (PMID 26918938, 2016). "Analysis of genetic context reveals an association between incidence of several somatic alterations, including IDH1 mutations in gliomas, and mtDNA content." (PMID 26901439, 2016). "IDH1/2 mutations were common in grade II-III gliomas (38–96 %), whereas TERT promoter mutations were frequently observed in oligodendrogliomas (74–83 %) and GBMs (58 %)." (PMID 27503138, 2016). "Most notably, cytosolic IDH1 is mutated in 70–90% of low-grade gliomas and upgraded glioblastomas, and mitochondrial IDH2 is mutated in ~20% of acute myeloid leukemia cases." (PMID 27014635, 2016). "IDH1 mutations were found in low-grade glioma and secondary glioblastoma, acute myeloid leukemia, chondrosarcoma, intrahepatic cholangiocarcinoma, and melanoma." (PMID 27863386, 2016). "Recent meta-analysis of 55 observational studies has shown that patients with gliomas positive for IDH1/2 mutations have improved both overall survival and progression-free survival, especially patients with WHO grade III and grade II-III tumors." (PMID 27379174, 2016). "IDH2 mutations were found in 0.5 % of pGBM (1/215), 3.4 % of sGBM (1/29) and 2.8 % (16/577) of low grade gliomas, while IDH1 mutations are found in 14.1 % (29/205) of pGBM, 55.2 % (16/29) of sGBM and 69.8 % (403/577) of low grade gliomas." (PMID 27245697, 2016). "Most grade II/III gliomas and secondary GBMs carry mutations in one of isocitrate dehydrogenase genes IDH1 or IDH2." (PMID 27693047, 2016). "Mutations in IDH1 have been reported in many types of tumors, e.g., gliomas, acute myeloid leukemias, and intrahepatic cholangiocarcinomas." (PMID 27469031, 2016). "The IDH1 mutation is one of the earliest known genetic events in low-grade gliomas, and it is thought to be a “driver” mutation for tumorigenesis." (PMID 27014635, 2016). "For example, IDH1 mutations are predominant in gliomas, chondrosarcoma, and cholangiocarcinoma, whereas IDH1 mutations and IDH2 mutations are equally common in AML." (PMID 27245697, 2016). "Recently described molecular markers, such as IDH1 mutation and 1p/19q co-deletion, are considered predictive of clinical outcomes for glioma patients." (PMID 27323413, 2016). "IDH1‐mutated gliomas have all been reported to have a single‐point mutation within the codon for Arg132." (PMID 27196610, 2016). "Current studies aim to validate and clarify the predictive value of IDH1 mutation in the different glioma types." (PMID 26858939, 2016). "Meanwhile, it was found that MGMT promoter methylation is a predictive marker for benefit from alkylating agents only in high-grade glioma patients with IDH1 wildtype, but 1p/19q loss in high-grade glioma patients with IDH1 mutant." (PMID 27733166, 2016). "Missense and truncating mutations of ATRX gene lead to loss of expression in gliomas and correlates with better clinical outcome in a subset of IDH1 mutant tumors." (PMID 27311324, 2016). "Evaluating 2-HG levels in astrocytomas and gliomas harboring various IDH1 mutations, Pusch and colleagues also showed that any mutations in IDH1 correlated with increased levels of 2-HG in human patient samples, a trend also observed by Juratli and colleagues." (PMID 26943899, 2016).
glioma (continued). "With respect to glioma, the functional illustration of (R)-enantiomer 2-hydroxygluterate (R-2-HG), produced through gain-of-function isocitrate dehydrogenase-1 (IDH1) mutations has fundamentally changed the way we approach these tumors." (PMID 26934654, 2016). "CIMP (CpG island methylator phenotype) is now recognized in many different tumor types and in the case of glioma is caused by mutations in IDH1/IDH2." (PMID 26646321, 2016). "The somatic mutations and aberrations are sometimes correlated, such as the link between IDH1 mutation and 1p/19q codeletion in low grade glioma." (PMID 26839018, 2016). "To investigate the different clinical and molecular characterization between IDH1 mutant and IDH2 mutant gliomas, we studied 811 patients with IDH1 mutations, IDH2 mutations and IDH1/2 wild-type." (PMID 27245697, 2016). "The IDH1-R132H mutation predicts a better clinical outcome for glioma patients, and the expression of IDH1-R132H correlates with a favorable outcome in patients with brain tumors." (PMID 27655638, 2016). "The major aim of this study was to determine the predictive role of ATRX for the presence of IDH1/2 or H3F3A mutations in gliomas showing ATRX loss." (PMID 27311324, 2016). "More than 70% of gliomas carry the mutation of IDH1 (R132H), which occurs in the critical arginine residue (Arg, R) in the catalytic pocket to histidine (His, H)." (PMID 27738332, 2016). "Houillier and colleagues stratified a cohort of low-grade gliomas into three groups based on prognostic factors according to the presence of 1p19q deletion, IDH1 mutation, or both together." (PMID 26858939, 2016). "Specifically, IDH1-mutated gliomas are a defined group of neoplasms that includes secondary glioblastomas and oligodendrogliomas." (PMID 27172899, 2016). "In gliomas and acute myeloid leukaemias, IDH1/2 mutations confer gain-of-function leading to production of the oncometabolite R-2-hydroxyglutarate (2HG) from αKG." (PMID 27624942, 2016). "Investigation of IDH1 mutation is associated with substantial challenges due to inability to culture in vitro primary glioma cells showing IDH1R132H." (PMID 27145078, 2016). "The survival benefit also extended to grade II gliomas, showing a median overall survival of 12.6 years in patients with IDH1 mutation versus 5.5 years in patients devoid of this mutation." (PMID 26858939, 2016). "The most frequent IDH-1 mutation type in glioma is R132H, which accounts for 88.2%-92.7% of mutations in this gene." (PMID 27120786, 2016). "In the presented study, we analyzed the MGMT methylation levels in 83 glioma patients with a known IDH1 mutation status and re-evaluated the clinical data with two years extended novel observations." (PMID 27834917, 2016). "Previous study by Pollack and colleagues reported that IDH1 mutation was common in adolescent malignant gliomas in which 16.3% of high grade gliomas between 3 to 21 years harbored the mutation and was significantly associated with age greater than 14 years." (PMID 26452024, 2016). "Expression of mutated IDH1 was found in 15 of 90 glioma tumors, whereas 4 of 57 cases in the glioblastoma subgroup were positive for mutated IDH1." (PMID 26839018, 2016). "The determination of IDH1 mutation status is highly relevant for the diagnosis of primary brain tumors, and strongly supports the differential diagnosis between an anaplastic glioma and a glioblastoma." (PMID 26858939, 2016). "The presence of activating IDH1 mutations (in low grade gliomas) or a large number of copy number alterations (in serous-like endometrial carcinomas) is strongly correlated to high tumor mtDNA content." (PMID 26901439, 2016). "In contrast to glioma and other cancer cells which express IDH1 mutations enhancing D-2-hydroxyglutarate production, this mutation has not been detected in RMS." (PMID 27144436, 2016). "The mutated form of the IDH1 gene leads to the epigenetic deregulation described as the ‘glioma CpG island methylator phenotype’." (PMID 26865861, 2016).
glioma (continued). "In this study, we established a highly sensitive antibody-based device, referred to as the immuno-wall, to detect the IDH1-R132H mutation in gliomas." (PMID 27877908, 2016). "The main prognostic variable for patients with glial tumors is the mutational status of IDH1 or IDH2." (PMID 27923049, 2016). "Nowadays, mutations in IDH1 are commonly established as a hallmark molecular feature of grade II/III gliomas and secondary GBM which have predominant ocalization in the frontal and temporal lobes." (PMID 27713914, 2016). "IDH1 wild type gliomas showed statistically lower Shannon entropy on T2WI than IDH1 mutated gliomas (Mean difference = 0.42, 95% confidence interval = 0.12 to 0.71, p = 0.007)." (PMID 27716832, 2016). "As well, the down–regulation of glutathione (GSH) in IDH1 mutated gliomas was suggested as a potential therapeutic target." (PMID 26820720, 2016). "Following Ohgaki and Kleihues, who found mutations of IDH1 as a “decisive genetic signpost” between the two glioma types, samples were separated based on the gene’s mutation." (PMID 27898674, 2016). "IDH1 mutation identifies GBMs that are developed from lower grade gliomas, i.e., secondary GBM, and are associated with prolonged patient survival." (PMID 26933808, 2016). "Lower grade (grade II-III) gliomas and secondary grade IV glioblastomas (arising from lower grade gliomas) display mutations in isocitrate dehydrogenase genes (IDH1/2) in 80 % of the cases." (PMID 27586084, 2016). "This compound can also reduce cellular D2HG concentrations and the colony-forming ability of glioma cells with IDH1 R132H mutation." (PMID 27316347, 2016). "Compounds 21 and 22 can also selectively impair colony-forming ability of patient derived glioma cells having R132H IDH1 mutation." (PMID 27316347, 2016). "Knowledges about beta-catenin regulation in glioma are recently increasing with R132H IDH1 mutation, FoxM1, TRIM33, HOXA13 as examples of positive or negative regulators." (PMID 27613837, 2016). "There is a mutation hotspot (R132H) in IDH1 in glioma and acute myeloid leukemia that is responsible for driving tumor progression." (PMID 27469031, 2016). "Increased overall survival for patients with glioma brain tumours is associated with mutations in the metabolic regulator isocitrate dehydrogenase 1 (IDH1)." (PMID 27820599, 2016). "In this study, we established a highly sensitive antibody-based device to detect the IDH1-R132H mutation in glioma." (PMID 27877908, 2016). "In 2008, the genes encoding IDH1 were found to be mutated in low-grade gliomas and a subset of sGBM." (PMID 27245697, 2016). "Approximately 69–80% of grade II and III gliomas harbor mutations in the isocitrate dehydrogenase 1 gene (IDH1), of which 83–90% are found to be the IDH1-R132H mutation." (PMID 27877908, 2016). "Although knowledge of tumor subtype has clinical utility, the best prognostic indicator for patients with glial tumors is the mutational status of IDH1 and IDH2." (PMID 27923049, 2016). "The origin of gliomas is suspected to locate among the glial progenitor cells and IDH1/2 mutations presumably initiate gliomagenesis." (PMID 27145078, 2016). "Characterization of the molecular landscape of lower-grade gliomas confirmed the presence of a known IDH1 mutation and 1p/19q codeletion (whole-arm loss of the long arm of chromosome 1 and the short arm of chromosome 19) and their role as a predictive markers." (PMID 27834917, 2016). "Twenty-two WHO grade 2 and 28 grade 3 glioma patients were collected whose pre-surgical MRI and IDH1 mutation status were available." (PMID 27716832, 2016). "Since IDH1-mutated tumors show a favorable patient survival and since the IDH1 status is considered to be an independent prognostic marker for WHO grade III gliomas, we decided to exclude IDH1-mutated samples from further analysis." (PMID 27158275, 2016).
glioma (continued). "In certain cancers especially glioma, mutations of the cytosolic (IDH1) or mitochondrial (IDH2) enzymes create a novel function in which they can further convert α-ketoglutarate to 2-hydroxyglutarate (2-HG)." (PMID 27358718, 2016). "IDH1 mutations affect cellular metabolism and are often present in gliomas, chondrosarcomas, and acute myeloid leukemias." (PMID 27655638, 2016). "The reported rates of IDH1 mutation in lower-grade gliomas are comparable with those of secondary glioblastoma." (PMID 26858939, 2016). "ATRX mutations were found to be restricted to IDH1/2 mutated glioma tumors and were also associated with better prognosis." (PMID 27698411, 2016). "The observed methylation pattern shows that CPEB1 belongs to the genes affected by the glioma associated CpG island methylator phenotype (G-CIMP) in IDH1/2 mutant tumors." (PMID 27256982, 2016). "Gliomas with IDH1 mutations have the neural stem cell phenotype and the adequate histone methylation profile." (PMID 27145078, 2016). "Isocitrate dehydrogenase 1 (IDH1) mutation and chromosome 1p/19q codeletion represent the most important molecular markers with clinical implications in lower-grade gliomas." (PMID 26369702, 2015). "The mIDH1-GL261 model we have used has obvious differences with human gliomas, as it is established in a malignant glioma while in humans IDH1 mutations take place early in development of low grade gliomas." (PMID 25849072, 2015). "In the current study, we collected 62 glioma patient tumor samples and detected IDH1(R132H) mutation with ddPCR and qRT-PCR." (PMID 26485760, 2015). "Astonishingly, D-2-HG accumulates to as high as 5 – 35 μmol/g (or 5 – 35 mM) in cases of glioma harboring IDH1/2 mutations." (PMID 25825982, 2015). "Collectively, we built a model for the genomic dynamics of clonal evolution during the malignant transformation in each case of IDH1-mutated glioma." (PMID 26524630, 2015). "IDH1 mutation has been observed as an early evidence and in high frequency (50%-93%) among astrocytomas, oligodendrogliomas, oligodendro-gliomas and secondary glioblastomas, while rarely occurs in primary glioblastoma." (PMID 27275230, 2015). "In glioma, ddPCR successfully measured the IDH1 mutations in extracellular vesicles and cerebrospinal fluid." (PMID 26485760, 2015). "Reduced expression of branched‐chain amino acid transferase 1 (BCAT1) in IDH1‐mutated gliomas has been shown, in part, to be caused by hypermethylation of the BCAT1 promoter region." (PMID 25864878, 2015). "Recent studies have defined the molecular classification of gliomas for clinical use, but we still look forward to a more convenient method for predicting prognosis based on IDH1/2 mutation status and Ki-67 expression level." (PMID 26338964, 2015). "Due to mutation frequency and importance of the modulation of glioma biology, an increasing effort has been placed on pharmacological targeting of mutated IDH1." (PMID 25849072, 2015). "Fifty-four of 55 studies investigated the association between IDH1/2 mutations and OS of patients with glioma." (PMID 26220714, 2015). "These two studies found that IDH1/2 mutations significantly improved the outcomes for patients with glioma." (PMID 26220714, 2015). "Recent work has reported that high Ki-67 expression is dominant in IDH1/2 wt gliomas and that low Ki-67 expression is associated with IDH1 mutations in primary GBMs." (PMID 26338964, 2015). "We studied 3 pairs of IDH1 mutated low grade gliomas and their high grade phenotype transformed after the lapse of time." (PMID 26524630, 2015). "The strongest prognostic factor for all glioma histologies is mutation in one of the isocitrate dehydrogenase genes (IDH1 or IDH2), and mutation of these genes is seen at higher frequencies in lower grade gliomas and secondary GBMs." (PMID 26091668, 2015). "The presence of mutated IDH1 is strongly correlated with a CpG island methylator phenotype in gliomas." (PMID 25790191, 2015).